PNPLA3 (patatin like domain 3, 1-acylglycerol-3-phosphate O-acyltransferase )
Diseases named in the same sentence as PNPLA3 in open-access papers (continued):
Sharing a sentence is not in itself a finding about the gene and the disease.
Hepatic steatosis (continued). "Second, comparison of rs1010023 and SNPs other than rs738409 may provide us with preferable understanding of PNPLA3 polymorphisms related to hepatic steatosis and glycolipid metabolism." (PMID 28695131, 2017). "A theoretic scenario is proposed that C-allele-dependent enzymatic loss of PNPLA3 hampers the TG transportation from hepatocytic lipid droplets to adipose tissues, with clinical features of liver steatosis and lowered serum level of TG, and then protects subjects from progressive obesity." (PMID 28695131, 2017). "Thus, PNPLA3 rs1010023 is indicated to underlie the occurrence of liver steatosis in chronic hepatitis B patients." (PMID 28695131, 2017). "When compared to the TT genotype, C-allele at PNPLA3 rs1010023 (CC and TC genotypes) conferred higher risk to hepatic steatosis in chronic hepatitis B patients (odds ratio (OR) = 1.768, 95% confidence interval (CI): 1.027–3.105; P = 0.045) independent of age, gender, and body mass index." (PMID 28695131, 2017). "It was reported in 2008 that a particular allele in PNPLA3 (I148M or rs738409) was strongly associated with increased hepatic steatosis and hepatic inflammation, with individuals homozygous for I148M exhibiting twice the level of hepatic fat content than non-carriers." (PMID 26978356, 2016). "For example, PNPLA3 rs738409 has been associated with the presence and severity of hepatic steatosis in numerous studies, independently of insulin resistance or inflammatory changes, lobular inflammation and perivenular fibrosis in both adult and paediatric NAFLD." (PMID 27314342, 2016). "Therefore the PNPLA3 I148M variant provides an example of how hepatic steatosis can occur in humans independently of insulin resistance and the metabolic syndrome." (PMID 26978356, 2016). "We might speculate that in non-adipose young patients with HIV/HCV coinfection other causes of liver steatosis such as HCV GT3 or metabolic factors might play a more important role than the PNPLA3 genotype." (PMID 26599080, 2015). "Both PNPLA3 genetic variants and BMI played important roles in hepatic steatosis in CHC patients." (PMID 26139292, 2015). "Both the PNPLA3 genetic variants and BMI determined hepatic steatosis." (PMID 26139292, 2015). "Recent studies have reported that a non-synonymous sequence variation (rs738409 C > G), which encodes an isoleucine to methionine substitution at position 148 (I148M) in PNPLA3, is associated with the susceptibility to fatty liver disease (FLD) and FLD-related liver fibrosis." (PMID 25337145, 2014). "Given the associations of PNPLA3 polymorphisms with liver steatosis and fibrosis in patients with chronic hepatitis C, we proposed that PNPLA3 polymorphisms might contribute to the progression of liver fibrosis and cirrhosis in CHB." (PMID 25337145, 2014). "Recently, the single-nucleotide polymorphism (SNP) of rs738409 patatin-like phospholipase domain-containing protein 3 (PNPLA3) has been identified for its significant associations with liver steatosis and fibrosis in patients with fatty liver disease and alcoholic liver disease." (PMID 23772356, 2013). "Association of PNPLA3 with not only fatty liver and TG content, but also inflammation and fibrosis were shown in the subsequent studies, so PNPLA3 may be widely associated with the development of NAFLD." (PMID 22719876, 2012). "Interestingly, Pnpla3 has been associated with fatty liver disease in humans: however the liver triglyceride concentration was unchanged in FtoI367F mice." (PMID 19680540, 2009). "PNPLA3 protein expression is increased in subjects with obesity compared to those without, while the presence of the rs738409 SNP encodes for a loss of function variant that promote triglyceride retention in lipid droplets, favoring the development of hepatic steatosis and enhancing inflammation." (PMID 39940335, 2025).
Hepatic steatosis (continued). "Moreover, exposure of these multilineage 3D spheroids to oestrogen receptor‐α (ERα/NR3A1) agonists showed an induction in PNPLA3 expression which further demonstrated how the interaction between ERα and PNPLA3 I148M‐carrier hepatocytes can drive fatty liver disease susceptibility in women." (PMID 39394864, 2025). "Additionally, rs2896019 (T > G) in PNPLA3 is associated with fatty liver." (PMID 39713746, 2024). "Our results highlight a specific context whereby the wild-type PNPLA3 facilitates the balance between hepatic triglyceride storage and secretion, and suggest the potential contribution of a loss-of-function by the I148M variant to the development of fatty liver disease in humans." (PMID 38844467, 2024). "Interestingly, Hispanics have a higher prevalence of fatty liver and of the PNPLA3 C > G variant, which may explain their increased risk of developing hepatic injuries and HCC, regardless of common metabolic risk factors." (PMID 36831120, 2023). "Analysis using a combination of molecular and genetic epidemiological approaches reveals an interaction between female sex and the genetic variant PNPLA3 p.I148M that might explain why some women have increased susceptibility to fatty liver disease after onset of menopause." (PMID 37749332, 2023). "Third, preliminary evidence suggests that the MAFLD definition might better capture patients who might benefit from an evaluation of genetic risks for fatty liver, as PNPLA3 rs738409 seems to be associated with MAFLD, but also with the development of kidney abnormalities." (PMID 35806010, 2022). "However, several genetic factors have also been implicated in the development of fatty liver, such as the I148M (rs738409) variant in the patatin-like phospholipase domain-containing protein 3 (PNPLA3) gene which showed the most clinically significant association." (PMID 33352841, 2020). "Because clinical conditions associated with hepatic steatosis are producing substantial health care costs, it is reasonable to assume that genetic variants in the PNPLA3 and TM6SF2 genes, as promoters of liver fat, might be associated with health care utilization." (PMID 26847197, 2016). "We assumed that the association between PNPLA3 rs738409 and health services utilization might be mediated by hepatic steatosis, ALT, ferritin, the metabolic syndrome, waist circumference, BMI, triglycerides, HDL, systolic blood pressure, serum glucose or hbA1c (models 3 to 13)." (PMID 26847197, 2016). "PNPLA3 rs738409 (I148M) genotypes may represent a genetic determinant of serum adiponectin concentrations and may be involved in mediating the susceptibility of liver steatosis." (PMID 24693952, 2014). "Recent studies found that subjects carrying the rs738409 PNPLA3 G-allele showed smaller adipocytes and suggested that this allele may contribute to the development of hepatic steatosis by modulating adipocyte size, which reflects the amount of lipid able to be stored in the subcutaneous fat depot." (PMID 23226254, 2012). "The factors included age, gender, BMI, T2DM, HT, DLP, AST, ALT, platelet count, liver steatosis grade, PNPLA3 rs738409, TM6SF2 rs58542926, and HSD17B13 rs6834314; as well as VCTE, M2BPGi, FIB-4, APRI, and NFS." (PMID 40002828, 2025). "Individuals with MAFLD-lean often possess specific genetic profiles, such as PNPLA3 or TM6SF2 risk alleles, and unique gut microbiomes that contribute to fatty liver development." (PMID 39955868, 2025). "Both PNPLA3 and TM6SF2 variants are associated with increased hepatic steatosis, more severe MASH, and advanced fibrosis/cirrhosis." (PMID 39860434, 2025). "According to genome-wide association studies (GWAS), some genes such as PNPLA3, TM6SF2, MBOAT7, GCKR, FTO, and HSD17B13 play important roles in metabolic pathways, especially liver steatosis and disease progression." (PMID 40864759, 2025). "Variant-specific associations included PNPLA3 with increased AST and MBOAT7 with higher hepatic steatosis (CAP)." (PMID 40943344, 2025).
Hepatic steatosis (continued). "Recent Phase I trials of AZD2693, a potent PNPLA3 ASO, displayed knockdown of PNPLA3 and significant reduction of hepatic steatosis in patients carrying the PNPLA3 I148M allele and presumed MASH with an acceptable safety and tolerability profile." (PMID 40589542, 2025). "Regarding advantages, the Pnpla3 I148M mice characterized by Pnpla3 I148M overexpression in the liver develop hepatic steatosis with increased levels of triacylglycerol and other lipids." (PMID 40004054, 2025). "PNPLA3 gene has been identified as a key genetic factor in the development and progression of fatty liver disease, influencing lipid accumulation and cellular changes that can lead to advanced liver conditions including cirrhosis and hepatocellular carcinoma." (PMID 40469136, 2025). "Genetic variations (PNPLA3, TM6SF2, GCKR, MBOAT7, MERTK, and HSD17B13) are one of the non-modifiable risk factors for metabolic dysfunction-associated fatty liver disease (MAFLD) and MASLD." (PMID 40507973, 2025). "Overall results suggest that the interaction of PNPLA3 I148M with ABHD5 on LD is required to promote liver steatosis." (PMID 39814233, 2025). "In contrast, overexpression of hPNPLA3 I148M in the liver or transgenic mice with the PNPLA3 I148M substitution develop liver steatosis." (PMID 39814233, 2025). "CRISPR–Cas9 experiments further demonstrated that this interaction drives lipid accumulation and fibrosis, establishing a direct link between ER-α and PNPLA3 p.I148M in the pathogenesis of fatty liver disease in women." (PMID 40677695, 2025). "PNPLA3 is a well-established genetic determinant of MAFLD, with the I148M variant strongly associated with liver steatosis and fibrosis." (PMID 41007773, 2025). "In Pakistani population, PNPLA3 variant rs 738408 with CT and TT genotype, and rs 738409 with GG genotype are associated with MAFLD and are at more risk for progression of this fatty liver disease towards its severity." (PMID 40469136, 2025). "The only genetic variation identified with a strong correlation to hepatic steatosis was Patatin-like phospholipase domain 3, PNPLA3 (rs738409)." (PMID 38539547, 2024). "PNPLA3 (148M) has also been reported to induce hepatic steatosis through the accumulation of PNPLA3." (PMID 38674929, 2024). "Moreso, in a chimeric mouse model with engrafted human hepatocytes, PNPLA3 I148M further increased hepatic steatosis in Western diet-challenged mice, providing further evidence for PNPLA3 I148M as a neomorph in the retention of hepatic TAGs." (PMID 38247511, 2024). "Despite the unclear mechanism through which PNPLA3 contributes to the accumulation of hepatic steatosis, it has been demonstrated to be involved in the remodeling of lipid droplets within hepatocytes and the secretion of very low-density lipoproteins." (PMID 38539547, 2024). "Pilot data (n = 18) indicated a greater reduction in hepatic steatosis in those with rs738409 PNPLA3 homozygosity (45%) than those with the CC following a 6 day hypocaloric, low-carbohydrate diet." (PMID 38717691, 2024). "Therapies that lower PNPLA3 levels can help correct hepatic steatosis in people with the PNPLA3(148M) variation." (PMID 38674929, 2024). "Under lipogenic conditions, mice with liver-specific knockout or acute knockdown of PNPLA3 exhibit aggravated liver steatosis and reduced plasma VLDL-triglyceride levels." (PMID 38844467, 2024). "The proportions of cases with different severities of hepatic steatosis in different genotypes of PNPLA3 rs738409 C>G were assessed (p = 0.001, FDR corrected p-value = 0.004)." (PMID 38674389, 2024). "It is interesting to note that mutations in PNPLA3, MBOAT7, and TM6SF2 are associated with fatty liver disease; however, TM6SF2 has a contrasting effect on CKD compared to mutations in PNPLA3 and MBOAT7." (PMID 38247511, 2024).
Hepatic steatosis (continued). "Polymorphisms in genes such as PNPLA3, TM6SF2, and GCKR promote steatosis through interaction with distinct metabolic mechanisms, predisposing to metabolic dysfunction-associated fatty liver disease." (PMID 38626012, 2024). "What’s more, the patatin-like phospholipase domain-containing 3 (PNPLA3) rs738409 gene is considered the strongest genetic determinant of fatty liver disease, is also highly expressed on renal podocytes and contributes to renal dysfunction." (PMID 38825630, 2024). "Reducing PNPLA3-I148M protein levels in the liver, including with I148M-specific siRNA, reduces fatty liver disease phenotypes, supporting a specific role for PNPLA3-I148M in driving MASLD (15, –17)." (PMID 38657050, 2024). "It was found that a variety of gene sites are related to the risk, disease severity, hepatic steatosis and advanced fibrosis of NAFLD, including PNPLA3, TM6SF2, GCKR, MBOAT7, APOC3, HSD17B13, etc.." (PMID 36973654, 2023). "Results of this study indicate that the interplay of birthplace and the presence of the PNPLA3 risk allele in overweight or obese Hispanic adults of Mexican descent could influence the association between the consumption of a traditional Mexican diet and hepatic steatosis." (PMID 38068856, 2023). "First, the most essential gene involved in the development of hepatic steatosis is the patatin-like phospholipase domain-containing 3 (PNPLA3)." (PMID 37447183, 2023). "Baicalin ameliorates alcohol-induced hepatic steatosis by suppressing SREBP1c-elicited PNPLA3 competitive binding to ATGL." (PMID 36636609, 2023). "Single‐nucleotide polymorphisms (SNPs) in PNPLA3 and hydroxysteroid 17‐beta dehydrogenase 13 (HSD17B13) genes are associated with fatty liver disease (FLD) progression and carcinogenesis." (PMID 37644826, 2023). "In line with this, mice fed the NASH-inducing diet and GalPLAC3-conjugated antisense oligonucleotide-mediated PNPLA3 silencing decreased liver steatosis." (PMID 36612019, 2022). "In a study to determine the causal relationship between steatosis and the development of liver damage, a PRS model was developed based on the risk alleles of four genes (PNPLA3, TM6SF2, GCKR, and MBOAT7) that were associated with hepatic steatosis." (PMID 36672614, 2022). "Increased PPAR-α activity has been shown to prevent the expression of SREBP-1c and lead to a decrease of patatin-like phospholipase domain=containing 3 (PNPLA-3), which is closely related to the risks of hepatic steatosis." (PMID 36555703, 2022). "PNPLA3 p.I148M and TM6SF2 p.E167K variants have been also associated to a higher risk of developing hepatic steatosis and advanced fibrosis." (PMID 35625751, 2022). "In these studies, the “G” allele of PNPLA3 has been implicated as a potential drug target for alcohol-related cirrhosis, Non-Alcoholic Fatty Liver Disease (NAFLD) and hepatic steatosis." (PMID 35330488, 2022). "Mechanistically, impaired clearance of this ubiquitination-resistant form of PNPLA3 promotes hepatic steatosis by accumulating on hepatic lipid droplets." (PMID 36499091, 2022). "Previous studies demonstrated that the patatin-like phospholipase domain containing 3 (PNPLA3; adiponutrin) p.I148M polymorphism is associated with liver steatosis." (PMID 36555467, 2022). "Imipramine increases fatty liver scores and is linked to adipogenesis in the liver, including FABP4 and SREBP1 mRNA levels, in addition to adiponectin, FASN, and PNPLA3 activation." (PMID 34564583, 2021). "Although, PNPLA3 rs738409 is the most common variant associated with risk of developing NAFLD, other nuclear genes have been linked to hepatic steatosis." (PMID 33532620, 2021). "PNPLA3 rs738409 and TM6SF2 rs58542926 are two well-studied SNPs where the minor alleles are reported to be associated with the development of HCC in fatty liver attributed to NAFLD or ARLD." (PMID 33808740, 2021).
Hepatic steatosis (continued). "The aim of this study isto evaluate the relationships between PNPLA3 and fatty liver, metabolic syndrome and subclinical atherosclerosis." (PMID 34833467, 2021). "Several studies have identified the fact that a common variant of the PNPLA3 gene (allele G rs738409) is strongly associated with NAFLD susceptibility and the degree of hepatic steatosis." (PMID 34833467, 2021). "PNPLA3-I148M has subsequently been associated with all aspects of NAFLD, including age at diagnosis; hepatic steatosis; disease severity; fibrosis stage; and HCC." (PMID 33544287, 2021). "We investigated interactions between a priori-selected dietary variables and PNPLA3 rs738409 in relation to levels of hepatic steatosis assessed by transient elastography (Fibroscan®) in a sample of MO adults with overweight or obesity." (PMID 34280991, 2021). "Consistently, Pnpla3I148M/I148M knock-in mice accumulate PNPLA3 on LDs and develop hepatic steatosis." (PMID 34503201, 2021). "The administration of an antisense oligonucleotide that mediated the silencing of the PNPLA3 gene demonstrated, in 148M/M mice, a reduction in liver steatosis although the mice were fed with a steatogenic high-sucrose diet." (PMID 34198853, 2021). "Although the PNPLA3 I148M in the pathology of fatty liver disease is well understood, further research is clearly needed to further expand the molecular mechanisms associated with these new findings and to further validate these results." (PMID 34476007, 2021). "For this reason, PNPLA3 is a good-looking target for therapeutic intervention aimed to avoid the progression of fatty liver disease towards the more critical stages." (PMID 34198853, 2021). "Single nucleotide polymorphisms (SNPs), including PNPLA3 rs738409 and SERPINA1 rs17580, have been identified as risk modifiers in the progression fatty liver disease (alcoholic (ALD) or non-alcoholic (NAFLD))." (PMID 33804385, 2021). "A common variant (Ile148Met) of Patatin-like phospholipase domain-containing protein 3 (PNPLA3), an ATGL homologue, has been reported to be an important risk factor for hepatic steatosis." (PMID 33036257, 2020). "Among AA in our MVP cohort, significant associations with NAFLD and/or ALT were detected for 6 variants, including PNPLA3 (rs738409) and PPP1R3B (rs4240624), which were previously reported in 3,124 AA patients examined for hepatic steatosis by CT." (PMID 32841307, 2020). "SLC30A10 and SLC39A8 encode metal ion transporters and PNPLA3 and TM6SF2 are known genes associated with fatty liver and cirrhosis." (PMID 32247823, 2020). "For example, PNPLA3 p.I48M and TM6SF2 p.E40K, although initially identified as associated with hepatic steatosis, strongly predispose to the development of alcoholic cirrhosis, non-alcoholic cirrhosis and hepatitis C-related cirrhosis." (PMID 32282858, 2020). "Next, we observed sporadic fatty liver phenotypes in Q140K+/+ males, but not WT animals and found in the same males altered gene expression in markers of fatty liver disease (Pnpla2, p = 0.012; Pnpla3, p = 0.050; and G6pd, p = 0.032, Student’s t-tests)." (PMID 32488095, 2020). "Murine models of fatty liver have unravelled significant insights into the mechanistic basis of PNPLA3-I148M induced steatosis." (PMID 31062641, 2019). "Pnpla3(148M) knockin mice also develop hepatic steatosis on the high-sucrose diet and hepatic inflammation and fibrosis on a NASH diet." (PMID 31921875, 2019). "Five fatty liver disease-associated SNPs (rs780094 (GCKR), rs2281135 (PNPLA3), rs8418 (PNPLA3), rs58542926 (TM6SF2), rs2980875 (TRIB1)) passed the significance threshold of <0.05 and were directionally consistent with previous studies." (PMID 30978214, 2019). "A sequence variation in patatin like phospholipase domain-containing protein 3 (PNPLA3), rs 738409, is strongly associated with the progression of fatty liver disease." (PMID 31062641, 2019).